PMS2 (PMS1 homolog 2, mismatch repair system component)
Description:
Component of the post-replicative DNA mismatch repair system (MMR). Heterodimerizes with MLH1 to form MutL alpha. Assembly of the MutL-MutS-heteroduplex ternary complex in presence of RFC and PCNA is sufficient to activate endonuclease activity of PMS2. It introduces single-strand breaks near the mismatch and thus generates new entry points for the exonuclease EXO1 to degrade the strand containing the mismatch. DNA methylation would prevent cleavage and therefore assure that only the newly mutated DNA strand is going to be corrected. MutL alpha (MLH1-PMS2) interacts physically with the clamp loader subunits of DNA polymerase III, suggesting that it may play a role to recruit the DNA polymerase III to the site of the MMR. Also implicated in DNA damage signaling, a process which induces cell cycle arrest and can lead to apoptosis in case of major DNA damages. Possesses an ATPase activity, but in the absence of gross structural changes, ATP hydrolysis may not be necessary for proficient mismatch repair.
Synonyms: PMSL2; H_DJ0042M02.9; HNPCC4; MLH4; PMS-2; LYNCH4; MMRCS4
Tractability: Small molecule: a structure with a bound ligand is known. PROTAC: ubiquitination databases record sites on it; its protein half-life has been measured.
Target class: Enzyme; Hydrolase
Gene: Protein-coding gene on chromosome 7 (5,970,925 to 6,009,130, reverse strand). Ensembl gene ENSG00000122512.
Subcellular location: Nucleus
Subcellular location (Human Protein Atlas): Nucleoplasm; Cytosol
Pathways (Reactome):
Disease: Defective Mismatch Repair Associated With MLH1; Defective Mismatch Repair Associated With PMS2
Gene Ontology:
Molecular function: ATP hydrolysis activity; DNA binding; MutSalpha complex binding; protein binding; single base insertion or deletion binding; single-stranded DNA binding; endonuclease activity; ATP binding; ATP-dependent DNA damage sensor activity; mismatched DNA binding
Biological process: meiotic mismatch repair; mismatch repair; somatic hypermutation of immunoglobulin genes; meiotic cell cycle; positive regulation of isotype switching to IgA isotypes; positive regulation of isotype switching to IgG isotypes; response to xenobiotic stimulus
Cellular component: MutLalpha complex; nucleoplasm; nucleus; mismatch repair complex
Genetic constraint (gnomAD): Loss-of-function variants: 37 observed, 54.22 expected, observed/expected ratio (o/e) 0.68, 90% interval 0.52 to 0.9. The upper end of that interval is the gene's LOEUF score, 0.9, which puts it in group 3 of 6, group 1 being the genes least tolerant of losing a copy. Missense variants: 721 observed, 748.64 expected, observed/expected ratio (o/e) 0.96, 90% interval 0.9 to 1.02. Synonymous variants: 244 observed, 276.56 expected, observed/expected ratio (o/e) 0.88, 90% interval 0.79 to 0.98.
Gene-disease validity (ClinGen):
ClinGen rates the evidence that PMS2 causes each of these diseases.
Lynch syndrome (autosomal dominant): Definitive. An autosomal dominant hereditary neoplastic syndrome characterized by the development of colorectal carcinoma and a high risk of developing endometrial carcinoma, gastric carcinoma, ovarian carcinoma, renal pelvis carcinoma, and small intestinal carcinoma.
mismatch repair cancer syndrome 1 (autosomal recessive): Definitive.
hereditary breast carcinoma (autosomal dominant): Disputed. Breast carcinoma that has developed in relatives of patients with history of breast carcinoma.
Cancer hallmarks: genome instability and mutations; escaping programmed cell death (suppresses); suppression of growth (promotes); escaping immune response to cancer; invasion and metastasis (suppresses); genome instability and mutations (suppresses); invasion and metastasis (promotes)
Homologues: Orthologues: chimpanzee PMS2 (98% identical), macaque PMS2 (95% identical), guinea pig PMS2 (81% identical), pig PMS2 (79% identical), dog PMS2 (78% identical), mouse Pms2 (78% identical), rat Pms2 (77% identical), rabbit PMS2 (66% identical), tropical clawed frog pms2 (62% identical), zebrafish pms2 (56% identical), Drosophila melanogaster Pms2 (41% identical), Caenorhabditis elegans pms-2 (33% identical). Paralogues in human: PMS1 (19% identical), MLH3 (18% identical), MLH1 (16% identical).
Diseases named in the same sentence as PMS2 in open-access papers:
PMS2 is named in the same sentence as 274 diseases in open-access papers, as found by Europe PMC text mining. Sharing a sentence is not in itself a finding about the gene and the disease. The quoted sentences say what the papers report.
Lynch syndrome (410 papers, 2007 to 2026). "Immunohistochemistry revealed loss of MLH1 and PMS2 expression, consistent with suspected Lynch syndrome." (PMID 41978784, 2026). "Compared to pathogenic variants in other MMR genes, PMS2-associated Lynch syndrome shows lower cancer susceptibility, with circa 10–13% lifetime risks for colorectal and endometrial cancer and relatively low incidence of other associated malignancies." (PMID 41528496, 2026). "MLH1 and PMS2 deficiencies are hallmark features of Lynch syndrome, with only rare instances of PMS2 loss of expression reported, typically resulting from MLH1 gene hypermethylation or somatic BRAF V600 mutations." (PMID 41170468, 2025). "Hematologic germline testing revealed heterozygosity for the pathogenic BRCA1 p.Lys918Serf∗82 variant and pathogenic PMS2 p.Cys843Tyr variant, consistent with hereditary breast and ovarian cancer syndrome and Lynch syndromes, respectively." (PMID 40948682, 2025). "This study demonstrates that biallelic somatic MLH1 mutations and constitutional MLH1 epimutations underlie MLH1/PMS2-deficiency in sebaceous neoplasms after excluding Lynch syndrome." (PMID 40208414, 2025). "The lesion also was noted to retain nuclear staining for PMS2 and MLH1, and is less likely to be related to any possible Lynch Syndrome, given that the patient also has a PMS2 deficient primary colorectal adenocarcinoma." (PMID 41035732, 2025). "PMS2 is generally considered a low to moderate penetrance cancer predisposition gene, typically associated with milder forms of Lynch syndrome." (PMID 41333974, 2025). "Among reported CMMRD cases, those associated with biallelic PMS2 variants are the most prevalent in literature, compared to presentations involving other Lynch syndrome-associated MMR genes." (PMID 41333974, 2025). "In contrast, heterozygous PMS2 variants are typically associated with lower penetrance and later-onset disease, with PMS2-associated Lynch syndrome (PMS2-LS) considered the mildest and the most frequently underdiagnosed form of LS documented to date." (PMID 41333974, 2025). "MMR protein immunohistochemistry showed loss of nuclear reactivity for MLH1 and PMS2, in keeping with Lynch syndrome and MSI-H/d-MMR status." (PMID 40341577, 2025). "Lower PMS2 expression in Lynch syndrome will lead to mismatch repair problems, which is a sign of susceptible genes in Lynch syndrome." (PMID 38200495, 2024).
Lynch syndrome (continued). "The proband was a DH PSV carrier in the CDH1 and PMS2 genes, which cause Hereditary Diffuse Gastric Cancer (and breast cancer) and Lynch syndrome, respectively." (PMID 39102164, 2024). "Through immunohistochemistry, we observed not only the loss of MLH1 but also of PMS2 protein, recognizing the typical pattern of Lynch syndrome due to MLH1 loss." (PMID 38368425, 2024). "Although PV/VLPs in PMS2 are relatively rare in the etiology of Lynch syndrome, these are known to increase an individual’s risk of developing colorectal cancer compared with the general population." (PMID 39656055, 2024). "This is a 70-year-old man with a history of Lynch syndrome with a germline mutation in PMS2 and castrate resistant PCa." (PMID 38879699, 2024). "PMS2 c.1376C>G was the most frequent Lynch syndrome-associated variant in a survey of Saudi CRC patients." (PMID 37306523, 2023). "It has long been thought that germline pathogenic PMS2 variant carriers (path_PMS2 carriers) represent only a small minority of Lynch syndrome (LS) patients." (PMID 36895471, 2023). "One of these patients had jejunal carcinoma, was already clinically suspected to have Lynch syndrome, and was immunohistochemically confirmed to have a PMS2 mutation during diagnosis." (PMID 36999887, 2023). "The large majority of germline alterations identified in the DNA mismatch repair (MMR) gene PMS2, a low‐penetrance gene for the cancer predisposition Lynch syndrome, represent variants of uncertain significance (VUS)." (PMID 35451539, 2022). "Generally heterozygous pathogenic variants in PMS2 display an attenuated Lynch syndrome phenotype consisting of lower penetrance and a later age at onset." (PMID 36421850, 2022).
Lynch syndrome (continued). "Mutations in PMS2 are linked to Lynch syndrome, which is characterized by early incidence of colorectal cancer, along with increased risk of other malignancies including endometrial, ovarian, small bowel, and brain carcinoma." (PMID 33503040, 2021). "Although studies on PMS2 variants are limited, the incidence of Lynch syndrome-associated tumors other than colorectal and endometrial cancers is low." (PMID 34185173, 2021). "PMS2 mutations have been rare in Lynch syndrome, probably due to difficulties in their identification, but more recently these have been reported, predisposing to endometrial cancer with a relative risk of about twice higher than for colorectal cancer." (PMID 34117277, 2021). "An individual carried a pathogenic variant in PMS2 (NM_000535.6) implicated in Lynch syndrome and the two patients carried each a variant in BRCA1 (NM_007300.3) or BRCA2 (NM_000059.3), associated with hereditary breast and ovarian cancer." (PMID 32231684, 2020). "Variant rs2228006 (PMS2) is common for hereditary nonpolyposis colorectal cancer type 4 and mismatch repair cancer syndrome." (PMID 32708070, 2020). "Half of the detected pathogenic/likely pathogenic variants were found in BRCA1 (23%), BRCA2 (23%), or the Lynch syndrome-associated genes PMS2 (4%) and MLH1 (2%)." (PMID 32090079, 2020). "Given the difficult diagnostic sequencing of PMS2, it is possible that some early onset Lynch syndrome cases supposedly caused by one pathogenic PMS2 variant are actually CMMRD with an unrecognized hypomorphic allele." (PMID 30740824, 2019). "A forth subclonal missense mutation in PMS2 P794S, previously reported in Lynch syndrome (ClinVar: 3 entries), was also present in both specimens." (PMID 31258848, 2019). "To aid scientific research and clinical development of PMS2 and its role in lynch syndrome, we share the gene- and pseudogene-specific variant information." (PMID 30268105, 2018).